MIR375 (microRNA 375)
Synonyms: hsa-mir-375; MIRN375; miRNA375; mir-375
Gene: MicroRNA gene on chromosome 2 (219,001,645 to 219,001,708, reverse strand). Ensembl gene ENSG00000198973.
Gene Ontology:
Biological process: miRNA-mediated post-transcriptional gene silencing
Cellular component: RISC complex
Homologues: Orthologues: chimpanzee ptr-mir-375 (100% identical), dog MIR375 (100% identical), guinea pig MIR375 (100% identical), macaque MIR375 (100% identical), mouse Mir375 (100% identical), pig ssc-mir-375 (100% identical), rabbit MIR375 (100% identical), zebrafish dre-mir-375-2 (73% identical), tropical clawed frog xtr-mir-375 (69% identical), zebrafish dre-mir-375-1 (69% identical), Drosophila melanogaster mir-375 (38% identical).
Diseases named in the same sentence as MIR375 in open-access papers:
MIR375 is named in the same sentence as 5 diseases in open-access papers, as found by Europe PMC text mining. Sharing a sentence is not in itself a finding about the gene and the disease. The quoted sentences say what the papers report.
breast carcinoma (1 paper, 2020). "Also, another study on populations suffering esophageal squamous cell carcinoma in Kazakh patients indicated that the variation in rs6715345 polymorphism of MIR375 gene leads to diminished risk of developing breast cancer." (PMID 32856881, 2020).
tumor (2 papers, 2023 to 2024). "Our study unveiled that the expression of MIR375 in tumor sites is significantly higher than that in normal tissue." (PMID 39104423, 2024). "Tumor tissues exhibited a significantly higher expression level of MIR375 than normal tissues." (PMID 39104423, 2024). "gov/), and the expression level of MIR375 was compared between tumor and normal tissues." (PMID 39104423, 2024).
MIR375 also shares sentences with these, for which no sentence is quoted: esophageal squamous cell carcinoma (1 paper); prostate carcinoma (1); tauopathy (1).